RNU7-69P (RNA, U7 small nuclear 69 pseudogene)
Synonyms: U7.69
Gene: Small nuclear RNA gene on chromosome X (123,772,078 to 123,772,139, reverse strand). Ensembl gene ENSG00000252178.
Homologues: Orthologues: chimpanzee U7 (100% identical), macaque U7 (95% identical). Paralogues in human: RNU7-13P (85% identical), RNU7-22P (85% identical), RNU7-3P (85% identical), RNU7-63P (85% identical), RNU7-11P (84% identical), RNU7-12P (84% identical), RNU7-28P (84% identical), RNU7-60P (84% identical), RNU7-6P (84% identical), RNU7-7P (84% identical), RNU7-8P (84% identical), RNU7-143P (82% identical), and 143 more.